ENSG00000279467 (novel transcript, antisense to SLC2A11)
Gene: Long non-coding RNA gene on chromosome 22 (23,865,248 to 23,873,277, reverse strand). Ensembl gene ENSG00000279467.
Gene Ontology:
Biological process: SRP-dependent cotranslational protein targeting to membrane, signal sequence recognition
Cellular component: signal recognition particle, endoplasmic reticulum targeting